TACC3 (transforming acidic coiled-coil containing protein 3)
Diseases named in the same sentence as TACC3 in open-access papers (continued):
Sharing a sentence is not in itself a finding about the gene and the disease.
bladder cancer (continued). "Briefly, TACC3 is involved in the development of bladder cancer and may serve as a promising prognostic biomarker in this cancer type." (PMID 29358577, 2018). "TACC3 levels are found to be altered in many human cancers including bladder cancer." (PMID 28855393, 2017). "Thus, we hypothesized that E2F1 may participate in the TACC3-mediated deregulation of the cell cycle and disease progression and may be responsible for the aggressive characteristics of bladder cancer." (PMID 29358577, 2018). "Previous pre-clinical studies have linked higher expression of neighboring genes to FAM53A on 4p16.3, including TACC3 and FGFR3, to bladder cancer development and progression." (PMID 39789109, 2025). "In bladder cancer, the FGFR3-TACC3 fusions TACC3 is a common partner that plays an important role in stabilizing and organization of the mitotic spindle to allow proper chromosome segregation." (PMID 37887311, 2023). "Primarily, we conducted a correlation analysis between the TACC3 mRNA level and the IC50 of cisplatin in bladder cancer cell lines using data downloaded from the CCLE." (PMID 29358577, 2018). "In summary, since TACC3 overexpression seems to indicate an aggressive phenotype, it is tempting to speculate that TACC3 would be a potential therapeutic target or a prognostic factor that could be used to predict therapeutic modalities and outcomes in bladder cancer." (PMID 29358577, 2018). "Third, rescue of mitotic defects in FT3-positive bladder cancer cells (RT112 and RT4) was possible either by knocking down FT3 or by low-level overexpression of full-length TACC3." (PMID 28855393, 2017). "In order to investigate the TACC3 removal effect further, we measured the endogenous TACC3 levels on the mitotic spindle in two different FT3-positive bladder cancer cell lines (RT112 and RT4)." (PMID 28855393, 2017). "In summary, our findings demonstrate that TACC3-PCAF competes with SIRT1 to bind c-Myc, enhancing its acetylation at K323 and thereby stabilizing c-Myc to promote colony formation and proliferation in bladder cancer." (PMID 40246827, 2025). "Future studies should explore whether TACC3 modulates PKM2 splicing or subcellular localization, thereby regulating its dual roles in bladder cancer progression." (PMID 40246827, 2025). "Furthermore, 12 out of 34 bladder cancer cell lines with E2F3 amplification, defined as log2(copy number) ≥1.3, exhibited higher levels of TACC3 mRNA expression." (PMID 40246827, 2025). "In addition, TACC3 is highly co-expressed with MCM4, CDC6, and CDC25A, indicated by correlation analysis using RNA-seq data of 42 bladder cancer clinical samples from our group published before." (PMID 29358577, 2018).
breast carcinoma (27 papers, 2005 to 2025). "In various cancers, including breast cancer, lung cancer, prostate cancer, and adult leukemia/lymphoma, TACC3 presents abnormal expression, and high TACC3 expression is usually associated with a poor prognosis." (PMID 38012214, 2023). "We used the DriverDBv3 tool to determine the mutation rate and CNVs distribution of TACC3 in breast cancer." (PMID 34149795, 2021). "TACC3 expression was positively associated with the clinical characteristics of breast cancer patients." (PMID 34149795, 2021). "Previous studies have also demonstrated that TACC1 was involved in endocrine therapy (tamoxifen and fulvestrant) resistance in breast cancer 27 and TACC3 was associated with chemoresistance (paclitaxel) in uterine cervical cancer." (PMID 27333920, 2016). "To date, high TACC3 expression has been shown to be associated with poor prognosis in several cancers such as non-small cell lung cancer, esophageal squamous cell carcinoma, hepatocellular carcinoma, gastric cancer, colorectal cancer, breast cancer, and cholangiocarcinoma." (PMID 29135996, 2017). "A rearrangement fusing exon 17 of the gene FGFR3 to exon 11 of TACC3 gene (1/140 – 0.7%) was detected with 184470 fusion mapped reads in patient operated for breast carcinoma brain metastasis." (PMID 39087020, 2024). "To test if TACC3 has a role in CC, we examined the correlation of TACC3 with a CC-related gene signature in breast cancer patients with CA." (PMID 36864125, 2023). "To support the mRNA- and gene signature-based analysis for TACC3 and CA, respectively, we stained TACC3 protein in breast cancer patients of all subtypes (BR1902, TissueArray) along with the centrosome marker, γ-tubulin to assess CA." (PMID 36864125, 2023). "Targeting TACC3 by guide RNAs or small molecule inhibitors strongly inhibits growth of organoids and breast cancer cell line- and patient-derived xenografts with CA by induction of multipolar spindles, mitotic and G1 arrest." (PMID 36864125, 2023). "Previously, KHS101 was shown to play a role in tumor therapy by down-regulating TACC3 levels in breast cancer, nasopharyngeal carcinoma and meningioma." (PMID 38012214, 2023). "We then used western blots to study the changes of EMT protein markers after TACC3 knockdown in breast cancer cells." (PMID 34149795, 2021). "To determine the role of TACC3 in breast cancer metastasis, we transfected T47D and SK-BR-3 cell lines with the control vector and TACC3 under-expression vector." (PMID 34149795, 2021). "To validate the biological interaction network of TACC3 in breast cancer, we identified genes co-expressed with TACC3 using the STRING database." (PMID 34149795, 2021). "To determine the role of TACC3 in breast cancer metastasis, we first transfected the T47D and SK-BR-3 cell lines with the control vector and TACC3 under-expression vector." (PMID 34149795, 2021). "To better understand the correlation and potential mechanisms of TACC3 expression in breast cancer, we investigated the relationship between the TACC3 expression and clinical characteristics of breast cancer patients using bc-GenExMiner 4.4." (PMID 34149795, 2021). "In the present study, we found that TACC3 was highly-expressed in breast cancer tissues, and its level was positively correlated with the clinical features of breast cancer patients." (PMID 34149795, 2021). "Taken together, these data indicate that TACC3 plays a role in the migration and invasion of breast cancer cells in vitro." (PMID 34149795, 2021). "From the GEPIA database, we found that TACC3 mRNA in breast cancer tissues (1,085 cases) was significantly higher than that in normal tissues (112 cases) (p < 0.05)." (PMID 34149795, 2021).
breast carcinoma (continued). "Taken together, these data indicate that TACC3 plays a role in the migration of and invasion by breast cancer cells in vitro." (PMID 34149795, 2021). "Despite these observations, the potential role of TACC3 and its molecular mechanisms in breast cancer remains to be addressed." (PMID 34149795, 2021). "The top three proteins (CKAP5, AURKA, and CDC20) interacting with TACC3 were verified by immunoprecipitation in breast cancer cells, and CKAP5, AURKA, and CDC20 were detected in the immunoprecipitation of anti TACC3 antibody." (PMID 34149795, 2021). "Growing evidence suggests that TACC3 is found overexpressed in many human cancers, including ovarian cancer, breast cancer, squamous cell carcinoma, and lung cancer." (PMID 27956147, 2017). "Amounting researches have indicated that overexpression of TACC3 can be found in various solid tumors, such as lung cancer, ovarian cancer, glioblastoma, breast cancer, and hepatocellular carcinoma." (PMID 29088887, 2017). "A more recent study has indicated that TACC2 and TACC3 are members of a set of 21 proteins that are strong prognostic indicators of clinical outcome in breast cancer." (PMID 15918899, 2005). "To experimentally demonstrate the role of TACC3 in CC, we selected two breast cancer cell lines with CA (HER2 + cell line, JIMT-1 and TNBC cell line, MDA-MB-231), and two non-CA cell lines (luminal A cell line, MCF-7 and TNBC cell line, MDA-MB-468) as negative controls." (PMID 36864125, 2023). "Furthermore, functional studies have shown that inhibition of TACC3 can significantly promote the cell proliferation and viability of breast cancer cells." (PMID 34149795, 2021). "Knockdown of TACC3 increased cell migration of breast cancer in vitro." (PMID 34149795, 2021). "Moreover, we investigated the mutation rate, single-nucleotide variation (SNV), copy number variation (CNV) distribution, and functional enrichment analyses of TACC3 in breast cancer." (PMID 34149795, 2021). "Together, these results demonstrated that TACC3 was highly expressed in breast cancer patients." (PMID 34149795, 2021). "The mechanism of TACC3 in breast cancer requires further study." (PMID 34149795, 2021). "Additionally, to confirm the differences in TACC3 expression in breast cancer, the expression of TACC3 was analyzed by using RNA-seq data from multiple malignancies in TCGA." (PMID 34149795, 2021). "TACC3 is highly expressed in breast cancer, but whether the downregulation of TACC3 represses tumorigenesis remains unknown." (PMID 34149795, 2021). "Taken together, these findings indicate that TACC3 may serve as a prognostic and therapeutic indicator of breast cancer." (PMID 34149795, 2021). "These clinical features were all consistent with the TACC3, a tumor-related gene of breast cancer, which indicates that KMO could serve as a potential diagnostic indicator in breast cancer as well." (PMID 34683090, 2021). "In conclusion, we found that TACC3 expression was upregulated in breast cancer tissues." (PMID 34149795, 2021). "In addition, TACC3 can be used as a biomarker with a potential role in breast cancer detection and for the prediction of clinical outcomes." (PMID 34149795, 2021). "Moreover, we used western blotting to study the changes of protein markers in TACC3-knockdown breast cancer cells." (PMID 34149795, 2021). "Inhibition of TACC3 in breast cancer induced apoptotic cell death." (PMID 31546954, 2019). "An up-regulation of Tacc3 was observed in breast cancer and it was suggested that Tacc3 might be a deregulator of DNA damage response and a predictor of survival for breast cancer patients." (PMID 28212608, 2017).
breast carcinoma (continued). "TACC3 was also observed to contribute to the chemosensitivity in breast carcinoma cells and NSCLC." (PMID 29088887, 2017). "In addition, TACC3 expression was suggested to be accelerated during the transition of breast cancer from ductal carcinoma in situ to invasive ductal carcinoma in microarray analysis." (PMID 29135996, 2017). "Our results suggest that TACC3 may serve as a potential target of breast cancer treatment." (PMID 34149795, 2021). "In contrast, Affymetrix microarray analysis has revealed that levels of TACC3 mRNA increase during the transition of breast cancer from preinvasive ductal carcinoma in situ to invasive ductal carcinoma, suggesting that TACC3 may impart a proliferative advantage to a subset of breast cancers." (PMID 15918899, 2005). "In a panel of breast cancer cell lines, we observed that the cancer cell lines with CA (mostly TNBC and HER2 + ) express higher levels of TACC3 and are more sensitive to TACC3 inhibition with BO-264." (PMID 36864125, 2023). "We demonstrated that TACC3 expression strongly positively correlates with KIFC1 mRNA, which is also correlated well with the CC score in breast cancer patients with high CA20 expression in the METABRIC dataset." (PMID 36864125, 2023). "However, the potential role of TACC3 in breast cancer remains largely unknown." (PMID 34149795, 2021). "We also investigated the possible relationship between TACC3, Notch4, and CDH5 in the proliferation of breast cancer cells." (PMID 34149795, 2021). "However, the potential role of TACC3 in breast cancer is still largely unknown." (PMID 34149795, 2021). "To verify the correlation between TACC3 and Notch4 and CDH5, we examined the RNA-seq data (N = 4,712) of breast cancer cohort in the TCGA database by using bc-GenExMinerv 4.4." (PMID 34149795, 2021). "Therefore, we hypothesized that TACC3 might serve as a biomarker for breast cancer research." (PMID 34149795, 2021). "The induced degradation of TACC3 when treated with ≥10 μM SNIPER(TACC3) resulted in apoptosis of both the fibrosarcoma (HT1080) and breast cancer (MCF7) cell lines and cell death was cancer cell specific, not affecting normal cell lines (TIG1 and MRC5)." (PMID 31500395, 2019). "Importantly, CA20 score and TACC3 levels were higher in HER2 + and basal subtypes of breast cancer, which are the two most aggressive subtypes." (PMID 36864125, 2023). "Because TACC3 knockdown can promote cell invasion of breast cancer, we speculate that TACC3 can affect the cell EMT process in breast cancer." (PMID 34149795, 2021). "Furthermore, we demonstrated that the TACC3 knockdown promoted cell proliferation, cell invasion ability, and EMT signaling pathways in breast cancer." (PMID 34149795, 2021). "We found that TACC3 was strongly expressed in breast cancer patient tissues, but negative in adjacent tissues." (PMID 34149795, 2021). "Knockdown of TACC3 upregulates the expression of Notch4 and CDH5, suggesting that TACC3 may be closely related to Notch4 and CDH5 signaling pathways in breast cancer." (PMID 34149795, 2021). "Therefore, the close interaction of TACC3 with CKAP5, AURKA, and CDC20 may suggest the role of TACC3 in the progression of breast cancer, although future mechanistic studies are needed to verify this possibility." (PMID 34149795, 2021). "Secondly, only miR-30e and miR-30c, but none of the other here identified miRNAs, were also found upregulated in another miRNA screen (data not shown) using MCF-7 breast carcinoma cells that undergo senescence following depletion of the centrosomal protein TACC3." (PMID 26895377, 2016). "Moreover, TACC3 knockdown suppressed the expression of E-cadherin, but increased the expression of N-cadherin, Snail, ZEB1, and TWIST, which indicate that TACC3 may impact the migration of breast cancer cells in vitro." (PMID 34149795, 2021).
breast carcinoma (continued). "However, TACC3 siRNA knockdown did not influence doxorubicin sensitivity in the breast cancer cell lines we tested, although we cannot rule out the possibility that this gene may contribute to the observed association with survival in vivo." (PMID 28179588, 2017).
cervical carcinoma (22 papers, 2005 to 2025). A carcinoma arising from either the exocervical squamous epithelium or the endocervical glandular epithelium. "Although mutations in EGFR in high-grade invasive cervical cancer are rare, it would be important to study an association between TACC3 expression and EGFR mutations." (PMID 23936413, 2013). "Several different cancers, and in particular, breast, ovarian, endometrial and cervical cancers exhibit loss of 4p16, the site of the TACC3 gene." (PMID 15918899, 2005). "Indeed, TACC3 has been implicated in a wide range of human cancers including multiple myeloma, lung cancer, cervical cancer, ovarian cancer, and esophageal cancer." (PMID 29358577, 2018). "We have previously proposed that TACC3 may be directly or indirectly associated with tumor progression and drug resistance of cervical cancer, based upon data acquired from microarray analysis to identify genes regulated by TACC3." (PMID 23936413, 2013). "Consistent with that idea, TACC3 is associated with EMT in both osteogenic sarcoma and cervical cancer." (PMID 30341253, 2018). "Other studies have shown that high TACC3 expression enhances the proliferation, migratory/invasive ability and transformation capacity of HeLa cervical cancer cells." (PMID 30341253, 2018). "It has been previously shown that TACC3 is involved in cervical cancer progression and can induce epithelial–mesenchymal transition by the activation of PI3K/Akt and ERK1/2 signal transduction pathways." (PMID 27956147, 2017). "In this study, we found that TACC3 was up-regulated upon EGF stimulation, and depletion of TACC3 abolished EGF-mediated EMT process in cervical cancer cells." (PMID 23936413, 2013). "We also immunohistochemically analyzed the expression of TACC3 using cervical cancer tissue microarrays." (PMID 23936413, 2013). "In this study, we found that TACC3 is overexpressed in cervical cancer and can be induced upon EGF stimulation." (PMID 23936413, 2013). "Our cervical cancer tissue microarray analysis revealed that the expression of TACC3 protein is up-regulated in cervical squamous cell carcinoma, the most common type of cervical cancer (approximately 80–90%)." (PMID 23936413, 2013). "TACC3 was almost undetectable in normal cervix, whereas its strong expression was observed in cervical cancer tissues." (PMID 23936413, 2013). "Surprisingly, the TACC3 inhibitor KHS10120 reduced not only wild-type TACC3 protein expression but also expression of the FGFR3-TACC3 fusion protein in FGFR3-TACC3 fusion-transfected cervical cancer cell lines, leading to suppression of phosphorylation of ERK and AKT." (PMID 29358619, 2018). "Collectively, our study highlights a novel function for TACC3 in EGF-mediated EMT process and suggests that targeting of TACC3 may be an attractive strategy to treat cervical cancers driven by EGF/EGFR signaling pathways." (PMID 23936413, 2013). "Herein, we demonstrate that TACC3 is overexpressed in cervical cancer." (PMID 23936413, 2013). "In this study, we aimed to investigate the functional significance of TACC3 in cervical cancer." (PMID 23936413, 2013). "Importantly, we found that the expression of Snail was elevated in cervical cancer and correlated with TACC3 expression." (PMID 23936413, 2013). "Moreover, Snail, a key player in EGF-mediated EMT, is found to be correlated with the expression of TACC3 in cervical cancer." (PMID 23936413, 2013). "Overexpression of TACC3 in cervical cancer was further confirmed in several cervical cell lines, including Ect1/E6E7 (HPV-16 E6/E7 transformed ectocervical epithelium), CaSki (HPV-16), C33A (HPV-negative), HeLa (HPV-18) and SiHa (HPV-16) compared with three normal human cervix tissues." (PMID 23936413, 2013). "Therefore, we questioned whether there is any correlation between TACC3 and Snail expression in cervical cancer." (PMID 23936413, 2013).
cervical carcinoma (continued). "TACC3 also promotes ERK and PI3K/AKT signaling, which induces the epithelial-mesenchymal transition (EMT), leading to cervical cancer initiation." (PMID 26219398, 2015). "TACC3 is involved in the Wnt/β-catenin and AKT pathways, which are involved in the EMT in cervical cancer." (PMID 26219398, 2015). "However, the upstream mechanisms of TACC3-mediated EMT and its functional/clinical importance in human cervical cancer remain elusive." (PMID 23936413, 2013). "TACC3 was previously suggested to piay a vital role in epidermal growth factor (EGF) mediated EMT, which represents a promising therapeutic strategy for the treatment of cervical carcinoma and is involved in the EGF/EGF receptor (EGFR) signal transduction pathway." (PMID 34134633, 2021). "Importantly, in the absence of TACC3, EGF is not able to induce EMT, suggesting that TACC3 is necessary for EGF-mediated EMT in cervical cancer." (PMID 23936413, 2013). "Moreover, we find a correlation between TACC3 and EGF inducer Snail in cervical cancer." (PMID 23936413, 2013). "However, TACC3 promotes epithelial-mesenchymal transition (EMT), which had been reported in osteogenic sarcoma and cervical cancer, haven't been observed in this study (data not shown)." (PMID 27248823, 2016).